DLG1 (discs large MAGUK scaffold protein 1)
Diseases named in the same sentence as DLG1 in open-access papers (continued):
Sharing a sentence is not in itself a finding about the gene and the disease.
scleroderma (1 paper, 2022). Scleroderma is a rare autoimmune connective tissue disorder characterized by abnormal hardening of the skin and, sometimes, other organs. "However, mesenchymal–epithelial transition (MET) associated proteins such as SCRIB, DSP, TJP1, CDH1, DLG1, and TJP2 were downregulated in scleroderma skin, indicating the high severity of skin fibrosis in mice with scleroderma." (PMID 35315234, 2022).
steatosis (1 paper, 2023). Increased lipid within the cytoplasm of cells. "P38γ can bind to Dlg1, a member of the membrane-associated guanylate kinase family, leading to liver injury, inflammation, and steatosis." (PMID 37755770, 2023).
Stroke (1 paper, 2023). Sudden impairment of blood flow to a part of the brain due to occlusion or rupture of an artery to the brain. "Investigations of PKP4, DLG1, DLG2, PTPRS and OBSL1 found insufficient evidence to provide a direct link between these genes and neurodegenerative or stroke events." (PMID 37422595, 2023).
ZIKV infection (1 paper, 2020). "The results showed that ZIKV infection significantly increased OAS2, IFIT3 and IFITM1 levels, and decreased Clorf27, DLG1 and EHBP1 levels." (PMID 32276512, 2020).
tumor (53 papers, 2004 to 2025). "Previous studies from our laboratory have demonstrated that there is a close association of Cx43 and Dlg1 in cultured tumour cells of a keratinocyte lineage and a direct interaction of the purified proteins in vitro." (PMID 37288673, 2023). "Dlg1 (PSD95 in mammals) is a tumor suppressor gene encoding a protein that localizes to intercellular junctions." (PMID 37145332, 2023). "DLG1 is a tumor suppressor which is associated with the establishment and maintenance of cell polarity." (PMID 35039052, 2022). "For example, dlg1 mutation facilitates tumor development and aPKC and Insc are crucial self-renewal factors during asymmetric stem cell division." (PMID 34830224, 2021). "Dlg1 is a well-characterized tumor-suppressor gene, loss of which leads to defects in proliferation and differentiation in multiple cell types." (PMID 30635267, 2019). "While the mechanism of activation is not understood, this function depends on a complex formed between E4-ORF1 and the membrane-associated cellular PDZ protein Discs Large 1 (Dlg1), a common viral target having both tumor suppressor and oncogenic functions." (PMID 24788832, 2014). "Interestingly, the loss of Dlg1 has been implicated in cancer progression across various tumor types highlighting the importance of its proper expression and/or localization." (PMID 40075218, 2025). "Recently, we showed that changes in the levels and cell distribution of DLG1 in HPV-associated lesions may have an important role in tumour progression." (PMID 32264889, 2020). "Dlg1 is one of four mammalian homologues of the Drosophila protein Discs large 1 (Dlg1), mutations in which cause tissue overgrowths typical of the loss of a tumour suppressor." (PMID 31289196, 2019). "It is the nuclear phospho-DLG1 forms that are preferentially targets for proteasomal degradation by HPV16 E6, suggesting that nuclear DLG1 may encode tumour suppressor activity." (PMID 26797638, 2016). "Our results show a slight increase in relocation of DLG1, suggesting that deregulation of normal DLG1 function is associated with disease progression; again, this supports the hypothesis of DLG1 acting both as a tumor suppressor and cell polarity regulator." (PMID 34503271, 2021). "Initial evidence indicating roles for DLG1 in cell growth regulation come from experiments in Drosophila, which demonstrated that the loss of DLG1 expression leads to uncontrolled epithelial cell proliferation and neoplastic transformation, suggesting DLG1 as a tumour suppressor." (PMID 32264889, 2020). "Beyond the nervous system, Dlg1 functions as a tumor suppressor protein and regulates epithelial cell polarity by modulating the formation of septate junctions." (PMID 41310158, 2025). "This raises the possibility that Dlg1 performs different roles in non-tumour and tumour cells, potentially demonstrating how HPV can alter the functions of cellular proteins to promote tumour progression and metastasis." (PMID 39522757, 2024). "The importance of Dlg1 as a tumour suppressor is further demonstrated by its targeting by at least three different oncogenic viruses; adenovirus type 9, human T-cell leukaemia virus-1 and HPV." (PMID 39522757, 2024). "Further immunoprecipitation experiments showed that Cx43 forms a complex with Dlg1 and E6 in HPV + ve tumour cells, while siRNA depletion of E6 restored Cx43 and Dlg1 at the cell membrane." (PMID 39522757, 2024). "Our results suggested that SF3B1 mutations in prolactinoma stimulate PI3K/AKT signaling by downregulating Discs large 1 (DLG1), which was induced by aberrant splicing to enhance tumor invasion and migration." (PMID 35039052, 2022). "In mammals, DLG1 appears to act as a tumor suppressor by affecting other polarity complexes, Myosin II activity, the actin cytoskeleton, and/or other signaling pathways." (PMID 35039052, 2022).
tumor (continued). "In summary, we found the SF3B1-R625H mutation activates the PI3K/Akt pathway in prolactinoma by aberrant splicing of DLG1, promoting tumor invasion progression." (PMID 35039052, 2022). "Furthermore, these PDZ-2 domain mutations in DLG1 seem to disable its interaction with the tumor suppressors APC and PTEN, emphasizing the importance of DLG1 functions and how alterations in its protein expression and localization might contribute to the process of oncogenesis." (PMID 34503271, 2021). "Like DLG1, SCRIB is a key player in cell polarity regulation and is a tumor suppressor, since loss of SCRIB leads to cancerous cellular overgrowth." (PMID 34503271, 2021). "In line with this, it is possible that such interaction not only abolishes DLG1 tumour suppression activities, but also stimulates potential oncogenic functions of DLG1, enhancing both viral replication and transformation." (PMID 32264889, 2020). "Due to the relevance of DLG1 deregulation in tumour development, we have performed an in-depth investigation of the expression of DLG1 in the presence of the HPV oncoproteins in epithelial cultured cells." (PMID 32264889, 2020). "Further research on this matter would provide a better comprehension of both HPV pathogenesis and the precise role of the differential expression of DLG1 in tumour progression." (PMID 32264889, 2020). "Due to the relevance of DLG1 deregulation in tumours, we have performed an in-depth investigation of the expression of DLG1 in the presence of the HPV oncoproteins in epithelial cells." (PMID 32264889, 2020). "One possible reason is that DLG1 dysregulation in advanced tumor progression or in more malignant forms depends on its spatial/temporal distribution." (PMID 32102656, 2020). "Like scrib, dlg1 is a tumor suppressor in the Scrib/Lgl/Dlg epithelial polarity module and mutant cells activate JNK." (PMID 30735120, 2019). "In this report, we carried out a series of analyses to investigate the nature of the aggregates, with a focus on the interaction of Tax with the PDZ protein DLG1, whose activities are important in tumor suppression and the HTLV-1 life cycle." (PMID 29168728, 2017). "This led to the idea that DLG1, whilst widely regarded as a tumour suppressor can acquire oncogenic characteristics in a different cellular context." (PMID 26797638, 2016). "In summary, we showed that in a mouse model of ocular adenocarcinoma, Dlg1, Scrib, and Lgl1 are present in the retina and tumor cells, albeit displaying different patterns of intracellular distribution in comparisons with normal mouse eyes of the same age." (PMID 19098995, 2008). "Both the mislocalization and downregulation of Dlg1, Scrib, and Lgl1 proteins seemed to be correlated to tumor progression, which was determined by the acquisition of new properties in cancer cells, in our mouse model of adenocarcinoma." (PMID 19098995, 2008). "At these stages, tumor cells invading the neural retina from the transformed RPE stained positive for Dlg1." (PMID 19098995, 2008). "Dlg1 also is a tumor suppressor gene in mice, such that Dlg1 heterozygous mice develop B-cell or NK cell lymphomas." (PMID 17042961, 2006). "Notably, CP proteins SCRIB and DLG1 are demonstrated to regulate the antigen presentation in DC, indicating that CP of cancer cells can modulate the polarized localization of tumor antigens to avoid recognition by DC or macrophages." (PMID 40057606, 2025). "DLG1 has historically been characterized as a tumor suppressor." (PMID 38789418, 2024). "Our data suggested that downregulating DLG1 expression promote tumor cell migration and invasion." (PMID 35039052, 2022). "Whether these effects on epithelial architecture modulate EGFR-RAS-ERK activation (perhaps through altering SCRIB/DLG1 function) or affect other signaling pathways to contribute to the tumor suppressor function of Tsp29Fb/TSPAN6 needs to be examined." (PMID 35184157, 2022). "Our studies indicated that knocking down DLG1 induced EMT in tumor cells." (PMID 35039052, 2022).
tumor (continued). "Future work comprehensively defining the how DLG1 activates the PI3K/Akt signaling pathway in tumor cell may therefore be very important." (PMID 35039052, 2022). "In this regard, even though DLG1 was initially identified as a tumour suppressor, it has been paradoxically shown to have pro-oncogenic functions when mislocalized and has been observed to accumulate in the cytoplasm of cancer cells from various different tumours." (PMID 36153517, 2022). "Tumor suppressors DLG1 and SCRIB are two of the principal PDZ domain-containing E6 targets." (PMID 34503271, 2021). "For example, DLG1 is a tumor suppressor gene whose knockdown in Drosophila leads to neoplasms in the developing brain and eye disc, while PAK2 is a key downstream mediator of the ERK signaling pathway for neuronal extension and is activated by caspases during apoptosis." (PMID 32053595, 2020). "The role of Dlg1 in human disease remains unclear, but immunohistochemistry staining of a variety of tumour types reveals that Dlg1 is often mislocalised to the cytoplasm." (PMID 31289196, 2019). "Dlg1, a tumour suppressor, is required for mitotic spindle orientation in Drosophila epithelia and chick neuroepithelia, but how Dlg1 is localised to the membrane and its importance in mammalian epithelia are unknown." (PMID 31289196, 2019). "The Drosophila ortholog of dlg1 was originally identified as a tumor suppressor and attenuator of cell division; thus alteration of its expression may affect cellular proliferation rates." (PMID 23028902, 2012). "DLG1 is the human homolog of the Drosophila lethal discs large-1 tumor suppressor." (PMID 21858148, 2011). "Only Dlg1 and Scrib proteins displayed an increased cytoplasmic distribution in tumor cells." (PMID 19098995, 2008). "Notably, this decrease in Scrib gene expression was observed at the same stage of tumor development as that corresponding to the decrease observed in Dlg1 mRNA levels." (PMID 19098995, 2008). "Specifically, we determined whether Dlg1, Scrib, or Lgl1 levels and distributions were altered during tumor progression." (PMID 19098995, 2008). "In addition to the reduced protein levels observed in western blots, we showed that immunostaining for Dlg1, Scrib, and Lgl1 in the inner nuclear layer was more diffuse for Trp1/Tag retinas during tumor development than for wild-type mouse retinas." (PMID 19098995, 2008). "In addition to its roles in maintaining cell polarity and acting as a scaffolding protein, Dlg1 has also been shown to have tumour suppressor functions through its interactions with adenomatous polyposis coli (APC) and phosphatase and tensin homologue deleted on chromosome 10 (PTEN)." (PMID 39522757, 2024). "In the first model, the tumour is induced via the GAL4-UAS mediated overexpression of RasV12 and Disc Large (Dlg1) RNAi in the eye." (PMID 38429578, 2024). "In the first model, the tumour is induced via the GAL4‐UAS mediated overexpression of RasV12 and Discs Large 1 (dlg1) RNAi in the eye." (PMID 38014610, 2023). "The discovery of DLG1 targeting by different viral oncoproteins, including HPV E6, has emphasized the role of DLG1 in tumour development." (PMID 32264889, 2020). "Among the genes differentially methylated are number of well- known tumor suppressor genes, namely RASSF1, DLG1, DLC1 and PRDM2, as well as various other tumor related genes." (PMID 24212793, 2011). "Upregulated genes were primarily associated with cell adhesion/invasion/metastasis (ELMO2, ADAM9, DLG1, TRPM7), metabolism/mitochondrial function (FAM120A, DARS2), and cellular transport/axonal trafficking (KIF1B, TBC1D5), indicating the presence of tumor microenvironment stress." (PMID 41404060, 2025). "It is worth exploring whether CP components like SCRIB and DLG1 affect the localization and function of major histocompatibility complex (MHC) molecules and other APMs in tumor cells." (PMID 40057606, 2025).
tumor (continued). "Dlg1 does not appear to perform a similar role in non-tumour epithelial cells, where Cx43 and Dlg1 colocalise at sites of cell-cell contact but show little colocalisation in the cytoplasm." (PMID 39522757, 2024). "We observed an increase in cellular relocation of DLG1 to the cytoplasm in tumor samples, regardless of HPV-presence, implying that deregulation of DLG1 normal function is likely to be linked with disease development." (PMID 34503271, 2021). "A positive relationship (Y = 1.6x + 0.00, p < 0.05) between DLG1 and LIN7C across tumor datasets could be confirmed, however distinct tumor clusters were not formed." (PMID 33726762, 2021). "Persistent dlg1 germ line clones develop into eggs, whereas follicle cells lacking dlg1 sometimes show tumor-like invasion into the interior of the egg chamber, a phenotype we did not observe in Dlg5 KD." (PMID 25795662, 2015). "While evidence indicates that Dlg1 has a tumor suppressor function, Dlg1+/+ but not mutant Dlg1−/− mouse embryo fibroblasts are able to support oncogenic PI3K activation by Ad9 E4-ORF1." (PMID 24788832, 2014). "Furthermore, DLG1 expression was shown to be low or even absent in the latest stages of tumour development in different cancers, which strongly suggest oncosuppressor functions." (PMID 32264889, 2020). "In line with this, the PBM-dependent binding of Human adenovirus E4-ORF1 to DLG1 results in the promotion of DLG1 oncogenic functions that contribute to E4-ORF1-mediated phosphatidylinositol-4,5-bisphosphate 3-kinase signaling activation, uncovering unexplored potential tumor activities of DLG1." (PMID 29168728, 2017). "Consistent with its tumor suppressive activity, the overexpression of Dlg1 in NIH-3T3 cells induces cell cycle arrest in G1, and this arrest can be overcome by Tax1 in a PBM dependent manner, indicating that Tax1, through direct binding, interferes with the growth-suppressive activity of Dlg1." (PMID 20017952, 2009). "Furthermore, DLG1 expression was shown to be low or even absent in the later stages of tumour development in different cancers, which strongly suggests that this cellular protein may have oncosuppressor functions." (PMID 36153517, 2022). "Additionally, a strong negative correlation between DLG1 mRNA levels and the expression of KDM5B was observedin PDAC tumor tissue." (PMID 38789418, 2024). "No linear relationship (Y = 0.66x + 0.08, p = 0.23) between DLG1 and LIN7B across tumor datasets could be confirmed." (PMID 33726762, 2021). "A weak linear relationship could be established between DLG1 and LIN7A, however no distinct tumor clusters could be formed." (PMID 33726762, 2021).
cancer (19 papers, 2008 to 2025). A tumor composed of atypical neoplastic, often pleomorphic cells that invade other tissues. "In this study, we found that DLG1 was significantly downregulated in PDAC cancer tissues with SMAD4 loss." (PMID 38789418, 2024). "Moreover, this expression pattern was the same as that observed in HPV-associated cervical lesions, where the mislocalization of DLG1 could have acquired oncogenic traits, contributing to cancer." (PMID 36153517, 2022). "Although the mechanism by which invading tumor cells survive the anoikis process remains largely unknown, we now know that the situation is rather more complex and that loss of Scrib and Dlg-1, which is often seen in malignant tumors, cooperatively contributes to the malignant state." (PMID 24093094, 2013). "DLG1 expression changes have also previously been noted in a number of different pathologies including cancer, neurological and immunological disorders." (PMID 37422595, 2023). "In short, only marginal changes in levels of DLG1 expression were seen in all three groups of HPV-negative OPSCCs when compared to cancer-free healthy tonsillar tissues." (PMID 34503271, 2021). "Despite the importance of this abnormal DLG1 redistribution during cancer development, the mechanisms behind this remain elusive." (PMID 32264889, 2020). "Our study is the first to demonstrate the involvement of Dlg1, Scrib, and Lgl1 proteins in a mouse of ocular adenocarcinoma and the simultaneous involvement of these proteins in a same cancer." (PMID 19098995, 2008). "Our results support the importance of intracellular mislocalization of Dlg1, Scrib, and Lgl1 during cancer development as suggested previously." (PMID 19098995, 2008). "This is the first study to demonstrate the involvement of Dlg1, Scrib, and Lgl1 in a mouse with ocular adenocarcinoma and the simultaneous involvement of these proteins in the same cancer." (PMID 19098995, 2008). "However, recently years, DLG1 has been found to be expressed differently among malignant tumors and to play a different role in the progression of tumors and sometimes even opposite role." (PMID 38789418, 2024). "In this regard, DLG1 deregulation to the cytoplasmic region has been shown to be important for HPV-positive carcinoma cell, as cytoplasmic DLG1 pools bound to E6 favor the activation of the GTPase RhoG, which in turn facilitates the invasive potential of these cells." (PMID 32264889, 2020). "Of the 18/21 samples that stained positive for DLG1, 8/21 showed low-intensity cytoplasmic staining, while 9/21 samples showed medium-intensity staining, similar to that observed in normal tonsillar tissue, and only 1/21 sample showed high-intensity staining in the majority of cancer cells." (PMID 34503271, 2021). "A few cancers or cancer-related genes [such as EPHA1 (OMIM*179610), MGLL (OMIM*609699), DLG1 (OMIM*601014), SLC49A4 (OMIM *602773)] have also been observed." (PMID 38540211, 2024).